CD4 (CD4 molecule)
Diseases named in the same sentence as CD4 in open-access papers (continued):
Sharing a sentence is not in itself a finding about the gene and the disease.
tumor (continued). "Moreover, immunofluorescence and immuno-histochemistry (IHC) images of tumor-infiltrating CD4+ T cells and CD8+ T cells confirmed the results of flow cytometry." (PMID 33420008, 2021). "Moreover, sunitinib suppresses the conversion of CD4+CD25- naïve T cells in Tregs in mouse tumor models." (PMID 33854498, 2021). "CD4 T cells can control tumor growth by cooperating with CD8 T cells to kill tumor stroma." (PMID 34201655, 2021). "Yu and his colleagues also showed us anti-CD40 agonist therapy could amplify immune-activated cDC1 subset, increase effector memory CD8+ CTLs, and induce the activation and expansion of TH1-like CD4+ T cells in MC38 tumor model." (PMID 33648605, 2021). "Thus, decreased tumor size was correlated with increased circulating CD4+ T cells in Alphataxin-treated mice and with increased circulating CD8+ T cells in anti-PD-1-treated mice." (PMID 34900690, 2021). "Based on our results, direct interference with tumor-infiltrating CD4+ T cells should also be considered and C1 inhibitor secretion by solid tumors could thus represent a new immune escape mechanism." (PMID 33808005, 2021). "Lastly, the tumor consists of a dynamic environment that may be affected by TCV-induced T cells overcoming immunosuppression via intratumoral activation of CD4 T cells and secretion of pro-inflammatory cytokines." (PMID 34290704, 2021). "Using strict definition of at least 60% difference in DNA methylation, we observed significant difference in the methylation pattern between GBM infiltrating CD4+ T-cells compared to the blood with ~75% of the DMRs were hypomethylated and ~25% were hypermethylated in tumor CD4+ T cells." (PMID 34012510, 2021). "For instance, tumor-infiltrating lymphocytes (TLS) such as CD4+ T cell and CD8+ T cell could remarkably improve the curative effects and survival rates." (PMID 35069691, 2021). "Similarly, adoptive transfer of interleukin-17 (IL-17) producing T helper 17 (Th17) cells was shown to induce durable anti-tumor immunity suggesting that polarization of CD4 T cells plays an important role in determining anti-tumor immunity." (PMID 34140957, 2021). "However, accumulating evidence reveals that CD4+ T helper (Th) cells have an important role in anti-tumour response." (PMID 32183246, 2020). "Flow cytometric analysis revealed that the tumor cells were CD4/CD8 DP." (PMID 32985581, 2020). "In addition, vaccination with Stat3∆/∆ CD103+ cDC1s elicited increased amounts of tumor antigen-specific CD8+ T cells and IFN-γ+ CD4+ T cells in tumors and tumor-draining lymph nodes versus phosphate-buffered saline (PBS)-treated animals." (PMID 31947933, 2020). "However, the lower production of pro-inflammatory cytokine TNFα and IFNγ in CD4+T cells or CD8+T cells in the tumor-bearing mice were significantly reversed by DMM treatment." (PMID 32596169, 2020). "Indeed, ex vivo experiments have shown that combined, rather than single blockade, of PD-1, Lag3 and Tim3, more efficiently rescues cytokine production and proliferative capacity of exhausted tumor-infiltrating CD4 and CD8 T-cells." (PMID 33207844, 2020). "However, their low infiltrating levels also indicate the impaired immune function in GBM; while tumor-infiltrating CD4+ T cells play the roles of a double-edged sword in tumor-specific immunity." (PMID 32133292, 2020). "Correlation analyses also demonstrated that CD8+ T-cells, CD8+ Tcm, CD8+ naive T-cells, CD4+ memory T cells, and CD4+ naïve T cells were all positively correlated with expressions of these inhibitory receptors in tumor tissues, especially with PD1 and CTLA4 (P < 0.05)." (PMID 32728493, 2020). "Interestingly, the combined depletion of CD8 and CD4 together partially restored tumor growth, suggesting that T lymphocytes, at least in part, play a major role in limiting tumor growth in RaptorECKO mice." (PMID 32759497, 2020).
tumor (continued). "Moreover, the infiltration numbers of CD8+ and CD4+ cells were also significantly enhanced in the tumours after the BP + aCD47 combination treatment compared to the control, thus triggering efficacious adaptive antitumour immunity." (PMID 33014356, 2020). "Indeed, studies demonstrate that pharmacologic and genetic inhibitions of Axl increased the number of tumor-infiltrating cDCs and the number of tumor-infiltrating CD4+ T-cells." (PMID 32660000, 2020). "Our results suggested that activation YAP1 dependent immune regulatory network may enhance the activity of resting CD4+T cells, thereby promoting tumor progression in PC." (PMID 33123286, 2020). "Palliative radiotherapy fractionation has been reported to be effective in HIV-seropositive patients with poor performance and advanced cancer, but having an intact immune system and a higher CD4+ count is a positive indicator to treatment response and reduction of tumour." (PMID 32276672, 2020). "Interestingly, the dihydropyrimidone derivative nifetepimine induced downregulation of SERCA3 expression, thereby protecting CD4+ T cells from tumour cell-induced cytotoxicity." (PMID 32825277, 2020). "This could explain why the benefits of CD4+ T cell infiltration on the prognosis of different tumours are somewhat inconsistent." (PMID 32758195, 2020). "Blastic plasmacytoid dendritic cell neoplasm (BPDCN), an extremely rare and aggressive tumor, derives from plasmacytoid dendritic cell precursors and is characterized by CD4 and CD56 positivity accompanied by the expression of isolated myeloid, B- or T-cell lineage markers." (PMID 33457326, 2020). "We observed lower PD-L1 and higher CD25 expression levels in CD4 T cells post-tumor resection." (PMID 32764562, 2020). "Also, the adoptive transfer of Ag-specific CD4+ T-cells in advanced CM patients can mediate durable complete tumor regressions." (PMID 32582212, 2020). "However, CD4+ T cells infiltrated more rapidly the tumor sites than CD8+ T cells during the tumor progression and, therefore, they became the dominant population in late stages of tumor development." (PMID 33312693, 2020). "Thus, more studies with human CD4+ T cells directly purified from fresh tumor tissues from OC patients should be performed in the future to explore the generality and applicability of this novel mechanism and therapeutic strategy." (PMID 33102225, 2020). "Regarding the critical importance of CD4 + T cell in the induction and maintenance of tumor antigen-specific CD8 + T cells, we assumed that low antigen specificity of conventional polyclonal DLI could be overcome by DEC." (PMID 32908796, 2020). "By increasing the mutation burden of tumor cells, oncogenic KRAS also induces the production of a large number of neoantigens that may be recognized by CD8+ and CD4+ T cells." (PMID 33194642, 2020). "The evidence here presented suggest therefore that the success of using HOCl-treated tumor lysates may partially lie in the induction and activation of a polyfunctional CD4+ T cell response." (PMID 32498431, 2020). "The role of CD4+ T cells and regulatory T cells in tumor immunity is more complex." (PMID 33033514, 2020). "Interestingly, when combined with αPDL1 therapy, their nanoparticle resulted in increased tumor cytotoxicity, lymphocyte trafficking to the tumor, and CD4 and CD8 T cell activation." (PMID 33260534, 2020). "Under normal circumstances, efferocytosis is a crucial process that prevents tissue inflammation; however, the clearance of dying cells’ remains by M2-like TAMs in the tumor microenvironment promotes immunosuppression through the inhibition of CD4+ and CD8+ T cells." (PMID 32326073, 2020). "Given that IL-17A-positive cells were mainly derived from the CD4+ cell population, Th17 cells may be the primary source of IL-17A in tumor tissues." (PMID 32503584, 2020). "Interestingly, it was shown that melanoma cells express MHC II on the cell surface, which allows them to attract tumor-specific CD4+ T-cells." (PMID 33256089, 2020).
tumor (continued). "In this work, we sought to elaborate T cell-mediated antitumor effects of tumor-redirected MHC class I-restricted CD4+ T cells in comparison to tumor-redirected CD8+ T cells and inquired possible synergistic effects of both subsets in our in vitro and in vivo models." (PMID 32610710, 2020). "Mutant KRAS could up-regulate immunosuppressive cells in tumor such as myeloid-derived suppressor cells (MDSCs), CD4+FoxP3+ T regulatory cells, and CD19+IL10+ B regulatory cells." (PMID 32206449, 2020). "Levels of both circulating and infiltrating DC correlates with better prognosis in both resectable and unresectable PC; furthermore, Fukunaka and coworkers reported a positive correlation between DC and CD4+/CD8+ tumor infiltration and an improved patient prognosis." (PMID 32012917, 2020). "Rigo and colleagues showed that combining CPi with temporary CD4 depletion by anti-CD4 monoclonal antibody (mAb) treatment caused a very potent CD8 T cell dependent response causing significantly longer tumor-free survival, complete tumor regression, and durable anti-NBL immunity in vivo." (PMID 32102342, 2020). "Furthermore, Blimp-1 and T-bet function as independent controllers of cytotoxic and helper activity in tumor-infiltrating CD4+ T cells, and both of these activities are critical to maximal anti-tumor activity of polyfunctional CD4+ Th-ctx cells." (PMID 31924474, 2020). "These clinical studies suggested that adoptive transfer of autologous or allogenic Vγ9Vδ2 T cell not only exert direct γδ T cell-mediated anti-tumor effect, but also promote and rescue the anti-tumor capacity of CD4+ and CD8+ T cells, suggesting a promising immunotherapeutic strategy." (PMID 32413966, 2020). "Hence, the depletion of CD4+Foxp3+CD25high Tregs from the peripheral circulation of the patients didn’t increase the efficacy of the DC vaccination against the tumor." (PMID 33519807, 2020). "Throughout this process, several naive T cells primed in the LN give rise to millions of differentiated T cells in the TME; many of these cells are subtypes of CD4+ cells (Th1, Th2, Th17, Treg, etc.), each of which plays a particular role in the anti-tumour immune response." (PMID 33276543, 2020). "A parallel analysis of spleens from tumor-bearing mice showed that CTX treatment was associated with a substantial decrease in B cells frequency overtime and a short-lived (i.e., day 3) depletion of CD4+ and CD8+ T cells." (PMID 32290265, 2020). "The recent past years have witnessed the surge of CD4 T cells into the scene of tumor immunity." (PMID 32244396, 2020). "In addition, elucidating the characteristics of CD8+ and CD4+ T cells, which are located in tumors and surrounding tissues, is also important, because they are major effectors that respond to ICIs and kill tumor cells." (PMID 33379384, 2020). "DCs, macrophages, and B cells present tumor antigens to CD4+ helper T cells." (PMID 33363026, 2020). "Reactivity of CD4+ T cells was generally low compared to CD8+ T-cell tumor reactivity." (PMID 32127601, 2020). "Interestingly, compared to the subcutaneously grown tumor, a smaller percentage of CD4+ T cells in the orthotopic grown tumor expressed markers (CD4+ CD39+ CD25+) for a regulatory T cell phenotype (28% vs. 15%, p ≤ 0.01)." (PMID 33383676, 2020). "Besides the systemic suppression by tumor-specific Tregs, the differentiation of naïve CD4+ T cells into T helper (Th) 1 or Th2, driving inflammatory and anti-inflammatory responses, respectively, influences cancer progression." (PMID 33207601, 2020). "Moreover, the number of tumour-infiltrating CD4+ and CD8+ T cells seemed to be lower in most rats that died soon after treatment." (PMID 32541941, 2020).
tumor (continued). "LXR agonist promotes the up-regulation of its transcription target ApoE, which binds to the LRP8 receptor on MDSCs, thus reducing the survival rate of MDSCs and increasing the CD8+ and CD4+ T cells activated by tumor invasion, reversing the tumor immune evasion, and promoting anti-tumor immunity." (PMID 33027968, 2020). "Importantly, the observed increase was restricted to the tumors, as we did not observe any marked differences in the levels of splenic CD8+ or CD4+ T cells suggesting the response is driven by specific tumor antigens in the tumors from Aire−/−." (PMID 32641748, 2020). "Moreover, infiltrating lymphocytes in sc tumor showed the same trend with statistical significance in CD4 (+) population." (PMID 32397971, 2020). "Reports have suggested that these EVs carried MHC complexes and T cell co-stimulatory molecules that could activate T cells and present their antigens, thereby stimulating antigen-specific CD8+ and CD4+ immune responses for tumor suppression." (PMID 33628730, 2020). "Furthermore, galectin-9 blockade expanded and activated tumor-infiltrating CD4+ and CD8+ T cells, but only in γδ T cell-competent hosts." (PMID 32055023, 2020). "The explanation for this controversy may be that CD4+ TILs are related to humoral immunity and play a major role in the tumour nest." (PMID 33170901, 2020). "CD4+ regulatory T cells are the main cells involved in self-tolerance and inhibit tumor immunity." (PMID 33816214, 2020). "A ligand may have also bound to VISTA on the CD4+T cell and stimulated cell differentiation into type 1 T helper cells, which play an important role in anti-tumor immunity." (PMID 33505908, 2020). "However, the CD4/CD8 ratio differs during tumor development with a predominance of CD8 + T lymphocytes (cytotoxic lymphocytes) in the early stages whereas CD4 + lymphocytes become predominant in late stages." (PMID 33026171, 2020). "In addition, the reduction of the CD8 and CD4 stromal signal, reaching significance in the extra-tumor immune component, further indicate that these tumors recruit less T lymphocytes." (PMID 32646072, 2020). "Tumor cells and tumor cell-derived cell lines in EBV-associated HL were found to have increased expression of the chemokine CCL20, which increased chemotaxis of immunosuppressive CD4+/CD25+ Treg cells in vitro." (PMID 33102204, 2020). "In addition to CD8+ CTLs, CD4+ T helper 1 (TH1) cells assist in tumor vessel normalization by producing IFN-γ in the TME." (PMID 32913278, 2020). "However, in the current study, the indirect role of CD4+T cells in killing tumor cells by secreting cytokines has been considered." (PMID 32148558, 2020). "Interestingly, paired tumor biopsies from the patient donor showed a similar reduction in the CD4/CD8 ratio after dual PD-1/CTLA4 blockade." (PMID 32331230, 2020). "Specifically, we found that platelet depletion in wild type animals resulted in significant inhibition of PD-L1 negative tumor growth and that this was associated with an increase in activated CD4+ and CD8+ cells within the tumor." (PMID 33168847, 2020). "Interestingly, depleting the Ly6G+ also reduced the number of CD4+-FoxP3+ cells in the tumor site, suggesting an alteration of tumor microenvironment upon depletion of LY6G+ cells." (PMID 32182988, 2020). "CD4+ T cell infiltration was also significantly enhanced by treatment, but this advantage was lost 3 weeks post-booster vaccination, although it should be noted that both anti-tumor CD4+ populations and TReg inhibitory CD4+ populations will be detected using this method." (PMID 32903551, 2020). "In this study, while the outcome obtained with the anti-PD-1 therapy was limited to a partial regression and correlated with an increased CD4+ Treg/CD4+ Th cells ratio, a complete tumor regression was achieved by the synergistic response when anti-PD-1 and anti-TGF-β antibodies were combined." (PMID 32733895, 2020).
tumor (continued). "Although both CD4+ and CD8+ T cell infiltrates were observed in tumors developed in TNFR1-deficient mice, only CD8+ T cells were significantly increased in the stroma of B16 tumor-bearing TNFR1 KO mice." (PMID 33202705, 2020). "In addition, CD4 T cells can indirectly kill tumor cells via directly activating antigen presenting cells (APC)." (PMID 32799890, 2020). "Interestingly, only in JNJ77-treated mice, the percentage of CD8+ T cells in TDLN negatively correlated with tumour weight, and the intratumoural ratio CD4+/CD8+ T cells positively correlated with tumour weight." (PMID 31748740, 2020). "In addition, the elimination of tumor-specific CD4+ T cells compromises secondary antitumor responses after successful primary immunotherapy, reinforcing the idea of a necessary CD4+ T cell help." (PMID 32582212, 2020). "In addition, we found that their expression levels were positively associated with infiltration of immune cells (CD4+T, CD8+T, B-cell, macrophages, neutrophils, dendritic cells) and tumor infiltrating lymphocytes (TILs)." (PMID 32508531, 2020). "Here, in pooled analyses with TCLs/TCLs + IFNγ and FTDs (n = 177), the proportion of tumor-reactive CD4+ TILs was similar across all cohorts, and tumor-specific CD4+ T cell responses were detected in over 50% of patients in each clinical cohort (range 58% in OC to 71% in RCC)." (PMID 33198174, 2020). "Specific Abs may be able to enhance inflammatory processes in the tumor and may also enhance CD4+ and CD8+ T cell responses by modulating antigen presentation." (PMID 31456339, 2020). "No matter how much low the frequency of TILs in the pMMR CRC tumor microenvironment is prior to any therapy, their presence provides some insight concerning the role of the cancer immunity cycle activation phase to prime antigen-specific CD4+ and CD8+ T-cells." (PMID 32090113, 2020). "Altogether our data suggest that the upregulation of TIM-3 on CD4+ TILs could alter the cells to have more immunosuppressive, migratory, and exhausted phenotype, which contribute to tumor evasion and metastasis." (PMID 32041340, 2020). "Indeed, expression of IFN-γ and TNF-α was increased in tumor-infiltrating CD4+ and CD8+ T cells of Lsp1 KO mice, while it was markedly reduced in those of Lsp1 Tg mice." (PMID 33020243, 2020). "This resulted in a more robust activation of CD8+ and CD4+ T cells and tumor regression without causing adverse events in vivo." (PMID 31921548, 2020). "Thus, the external stimulation with cancer vaccines will be critical in strengthening the immunogenicity of tumor antigen, stimulating anti-tumour immunity, enhancing CD4+ and CD8+ T-cell populations and promoting Th1 cytokine secretion." (PMID 32737343, 2020). "Since PD-L1 was enriched in the adjacent stroma rather than in the tumor nest, to systematically analyze the TIME in PESCCs, where PD-L1 expression is enriched, we performed H&E staining and IHC analysis of CD4+ and CD8+ TILs and CD163+ tumor-associated macrophages (TAMs) in all 81 patients." (PMID 33457428, 2020). "Moreover, the tumor-infiltrating levels of the T cell types except exhausted CD4 + T cell and tumor Treg." (PMID 33133170, 2020). "We speculate that the release of the immunosuppression that had been induced by the PD-1/PD-L1 interaction would give rise to the activation of a remaining pool of naïve CD4+ cells and the subsequent enhancement of the anti-tumor immune activity." (PMID 31968651, 2020). "This may be due to direct recognition of vaccine-derived antigen by the anergic CD8+ T cells, or indirectly due to the induction of antigen-specific CD4+ T cell help, which can also override tumor-induced peripheral tolerance and trigger tumor control." (PMID 33072137, 2020).